MIR758 (microRNA 758)
Synonyms: hsa-mir-758; MIRN758; mir-758
Gene: MicroRNA gene on chromosome 14 (101,026,020 to 101,026,107, forward strand). Ensembl gene ENSG00000211582.
Homologues: Orthologues: chimpanzee ptr-mir-758 (100% identical).